CRP (C-reactive protein)
Description:
Displays several functions associated with host defense: it promotes agglutination, bacterial capsular swelling, phagocytosis and complement fixation through its calcium-dependent binding to phosphorylcholine. Can interact with DNA and histones and may scavenge nuclear material released from damaged circulating cells.
Synonyms: PTX1
Tractability: Small molecule: a structure with a bound ligand is known; it has a high-quality binding pocket. Antibody: UniProt places it where antibodies can reach, with medium confidence; UniProt predicts a signal peptide or a membrane-spanning region; its Gene Ontology location is reachable by antibodies, with medium confidence.
Gene: Protein-coding gene on chromosome 1 (159,712,289 to 159,714,589, reverse strand). Ensembl gene ENSG00000132693.
Subcellular location: Secreted
Subcellular location (Human Protein Atlas): Nucleoplasm; Vesicles; Intermediate filaments; Predicted to be secreted
Pathways (Reactome):
Immune System: Classical antibody-mediated complement activation
Gene Ontology:
Molecular function: calcium ion binding; complement component C1q complex binding; identical protein binding; low-density lipoprotein particle binding; low-density lipoprotein particle receptor binding; protein binding; virion binding; choline binding
Biological process: negative regulation of lipid storage; negative regulation of macrophage derived foam cell differentiation; negative regulation of mononuclear cell proliferation; positive regulation of gene expression; positive regulation of superoxide anion generation; regulation of interleukin-8 production; vasoconstriction; acute-phase response; defense response to Gram-positive bacterium; inflammatory response; innate immune response; opsonization
Cellular component: extracellular region
Genetic constraint (gnomAD): Loss-of-function variants: 7 observed, 4.67 expected, observed/expected ratio (o/e) 1.5, 90% interval 0.79 to 1.93. That is too few expected variants to judge how well the gene tolerates losing a copy. Missense variants: 297 observed, 283.1 expected, observed/expected ratio (o/e) 1.05, 90% interval 0.95 to 1.15. Synonymous variants: 130 observed, 116.81 expected, observed/expected ratio (o/e) 1.11, 90% interval 0.96 to 1.29.
Homologues: Orthologues: chimpanzee CRP (99% identical), macaque CRP (91% identical), rabbit CRP (75% identical), guinea pig CRP (73% identical), mouse Crp (70% identical), pig CRP (67% identical), dog CRP (61% identical), tropical clawed frog crp.2 (44% identical), tropical clawed frog apcs.2 (43% identical), tropical clawed frog apcs (42% identical), tropical clawed frog XB5856184 (39% identical), tropical clawed frog crp (37% identical), and 2 more. Paralogues in human: APCS (51% identical), NPTX2 (29% identical), PTX3 (25% identical), NPTX1 (25% identical), PTX4 (25% identical).
Diseases named in the same sentence as CRP in open-access papers:
CRP is named in the same sentence as 1,906 diseases in open-access papers, as found by Europe PMC text mining. Sharing a sentence is not in itself a finding about the gene and the disease. The quoted sentences say what the papers report.
COVID-19 (4,228 papers, 2020 to 2026). A disease caused by infection with severe acute respiratory syndrome coronavirus 2. "The serum level of C-reactive protein (CRP) is a significant independent risk factor for Coronavirus disease 2019 (COVID-19)." (PMID 38184750, 2024). "It was considered in a randomized clinical study as a possible treatment for COVID-19-associated pneumonia and high CRP levels." (PMID 36906872, 2023). "Coronavirus disease 2019 is a systemic disease characterized by a cytokine storm associated with high levels of C reactive protein (CRP), high fibrinogen, high fibrin degradation to D-Dimers, microvascular injury, and obstructive thrombo-inflammatory syndrome." (PMID 36519165, 2022). "The multivariate ordinal logistic analysis after adjusting for gender, vaccination date, and vaccination dose indicated that CRP at Days 4−7 and 8−14, IL‐6 on Days 4−7, and total antibody were risk factors for coronavirus disease 2019 severity." (PMID 35759224, 2022). "Levels of SARS-CoV-2 viremia was also associated with markers of inflammation and disease severity, including low lymphocyte counts, and elevated CRP and IL-6 levels." (PMID 33127906, 2020). "CRP, an indicator of inflammation, is particularly elevated in cytokine storm that can occur in COVID-19 patients and is associated with disease mortality." (PMID 40807003, 2025). "Several studies have linked elevated hs-CRP levels to less favorable clinical outcomes in COVID-19 patients, dictating its potential as a biomarker for predicting clinical severity." (PMID 40933377, 2025). "In COVID-19 cohorts, higher CRP concentrations have been tightly linked to elevated IL6 and to worse outcomes, including respiratory failure, intensive care unit (ICU) admission, and mortality." (PMID 41373577, 2025). "linked elevated D-dimer relative to C-reactive protein in acute COVID-19 to subjective cognitive deficits and occupational impact in PACS patients." (PMID 40547035, 2025). "The high level of D-dimers, indicating an increased hypercoagulation, together with elevated levels of IL-6 and CRP, indicating sustained inflammation, are associated with an increase in infection, sepsis, and mortality in COVID-19 patients." (PMID 40149514, 2025). "In terms of laboratory and clinical findings, our results indicate that 19% of COVID-19-positive patients had elevated CRP levels, particularly in severe cases associated with pneumonia." (PMID 39998062, 2025). "The severity of COVID-19 acute infection was associated with increased levels of CRP, ferritin and LDH during follow-up (p < 0.001)." (PMID 41595620, 2025). "Baseline data were supplemented with clinical findings known to be risk factors for acute COVID-19, such as C-reactive protein and peripheral blood neutrophil:lymphocyte ratio." (PMID 40429360, 2025). "Elevated levels of inflammatory markers, such as LDH, KL-6, ferritin, D-dimer, CRP, and IL-6, as well as decreased lymphocyte counts, have been reported to be associated with poor outcomes in patients with COVID-19." (PMID 40575188, 2025). "Consistent with previous studies, we found that both CRP and IL-6 were associated with worse outcomes from COVID-19 including mortality and requirement for 10-day intubation." (PMID 39969178, 2025). "We observed that patients with PCPF had significantly higher hemoglobin levels and CRP during the acute phase of COVID-19, both of which were independently associated with fibrosis in the multivariate analysis." (PMID 41277954, 2025). "Elevated serum levels of IL-6 and CRP as inflammatory markers are associated with the severity of COVID-19 and can be used as a prognostic marker of the disease." (PMID 40978940, 2025). "The high level of D-dimers, which relate to hypercoagulation, combined with elevated levels of IL-6 and CRP, which reveals sustained inflammation, is most likely associated with increased infection, sepsis, and mortality in COVID-19 patients." (PMID 40149514, 2025).
COVID-19 (continued). "Several biomarkers have been associated with the severity of COVID-19, including D-dimer, C-reactive protein, ferritin, and lactate dehydrogenase." (PMID 40559088, 2025). "COVID-19 causes significant inflammation in the body, resulting in high CRP, ferritin, CPK, and lactate dehydrogenase, as seen in this patient." (PMID 40656321, 2025). "The administration of NAC (30,000 mg i.v. in 2 days) alleviated hemolysis and decreased COVID-19-associated increases in liver enzymes, C-reactive protein (CRP), and ferritin in the G6PD-deficient patient." (PMID 40141299, 2025). "We observed that lung adenopathy was linked to increased neutrophil counts and higher levels of CRP, further emphasizing the role of inflammation in the development of lymph node enlargement in COVID-19 patients." (PMID 40428888, 2025). "The progression of COVID-19 has been associated with elevated plasma levels of acute-phase reactants, including C-reactive protein (CRP), IL-6, D-dimer, and procalcitonin." (PMID 40869381, 2025). "This study aims to addresses two important gaps in knowledge by comparing novel inflammatory markers (HBP and SAA) against established markers (IL-6 and CRP) to characterize inflammatory phenotypes associated with tissue damage and viral load in COVID-19." (PMID 40621180, 2025). "Several studies have already shown the importance of high levels of laboratory markers, such as bilirubin, D-dimer, C-reactive protein, urea, and others, associated with the severity of COVID-19." (PMID 39861879, 2025). "In our study, elevated inflammatory markers, including CRP, ferritin, and D-dimer, were significantly associated with severe COVID-19 outcomes." (PMID 40469148, 2025). "Compared to females, IL-6 (Mann–Whitney U = 2653, p = 0.0241) and CRP (Mann–Whitney U = 7350, p = 0.0055) were increased in omicron-variant COVID-19 male patients, while IL-6 also increased in the delta variant (Mann–Whitney U = 3200, p = 0.0254)." (PMID 40868247, 2025). "As expected for the underlying condition, the COVID-19 positive group exhibited elevated inflammatory markers, including CRP, ESR, IL-6, and ferritin, alongside reduced absolute lymphocyte counts." (PMID 40733560, 2025). "The significant association between CRP levels and poor outcomes in our study (OR = 1.010, p = 0.027) is consistent with previous research emphasizing the role of inflammation in COVID-19 progression." (PMID 40284898, 2025). "At the height of the COVID-19 pandemic, risk stratification was based on simple clinical parameters (age, comorbidities, etc) as well as markers of inflammation such as CRP and IL6." (PMID 40173171, 2025). "In the context of COVID-19, significant risk factors for venous thromboembolic complications are male predilection, older age, mechanical ventilation, elevated C-reactive protein and increased D-dimer levels." (PMID 41383156, 2025). "Elevated CRP has been identified as a key marker in severe COVID-19 progression, while high D-dimer levels are often associated with thromboembolic events, a frequent complication among severe cases." (PMID 40860652, 2025). "Hyperglycemia is associated with increased cytokine storm - IL-6 and CRP levels - and immune dysfunction - decreased lymphocytes, and T cells - in COVID-19." (PMID 40314776, 2025). "The severity of COVID-19, according to the literature, is most significantly associated with high levels of CRP, LDH, WBC, and RDW and the presence of lymphopenia and eosinopenia." (PMID 40143356, 2025). "Threshold effect analysis of hs-CRP on 10-year CVD risk progression in T2DM patients infected with COVID-19." (PMID 40933377, 2025). "COVID-19 is closely associated with various hematological abnormalities, including lymphopenia, elevated inflammatory markers such as C-reactive protein (CRP) and ferritin levels, as well as abnormalities in the coagulation pathway." (PMID 40034745, 2025).
COVID-19 (continued). "Clinical inflammatory markers linked with N protein levels, such as elevated CRP and sustained levels of cytokines like IL-6, have also been associated with prolonged recovery time in COVID-19 patients." (PMID 40872762, 2025). "The results of our study showed that previous COVID-19 and CRP were the factors associated with coronary artery restenosis." (PMID 40428011, 2025). "Increased IL-6 levels have been consistently associated with disease severity in COVID-19 patients, as have higher concentrations of C-reactive protein, a downstream inflammatory marker." (PMID 40572294, 2025). "Previous studies have shown that elevated fibrinogen levels in COVID-19 patients are significantly associated with increases in inflammatory markers such as interleukin-6, C-reactive protein, ferritin, erythrocyte sedimentation rate, and procalcitonin." (PMID 40791995, 2025). "Elevated serum CRP levels in COVID-19 patients are positively associated with both circulating N antigen levels and COVID-19 severity." (PMID 40872762, 2025). "The CRP levels which were found to have statistically significant association with COVID-19 severity (<0.05)." (PMID 38905361, 2024). "The objective of this study was to evaluate the association between plasma C-reactive protein (PCr) on hospital admission and mechanical ventilation requirement during hospitalization in adults with COVID-19." (PMID 38537098, 2024). "The VD of the SCP was linked to the high levels of C-reactive protein measured during the acute phase of COVID-19." (PMID 38343644, 2024). "As a result of CRP-mediated neutrophil macrophage activation, COVID-19 causes pulmonary fibrosis and eventual organ failure." (PMID 38184750, 2024). "The CRP rs1800947 GG genotype (P < 0.0001, OR 7.96, 95% CI 6.21–10.21) was associated an increased chance to COVID-19 mortality." (PMID 38184750, 2024). "Our study highlights the association of biomarkers such as CRP, serum ferritin, and IL-6 with renal injury in COVID-19 patients." (PMID 38975470, 2024). "In conclusion, this study showed that COVID-19 mortality rate was correlated with CRP rs1205 TT genotypes and CRP rs1800947 GG genotypes across all three variants." (PMID 38184750, 2024). "Elevated CRP levels have been associated with severe infection, increased inflammatory changes in chest CT scans, and increased mortality in patients with COVID-19." (PMID 39335569, 2024). "Most patients reported as having developed COVID-19 associated hiccups have been found to have high levels of inflammatory markers such as C-reactive protein." (PMID 38890624, 2024). "The increase in CRP was inversely statistically associated with the tendency of serum potassium to decrease at discharge in patients with type 2 diabetes and COVID-19." (PMID 38929867, 2024). "Elevated levels of CRP and D-dimer in patients with COVID-19 are also associated with an increased risk of thrombosis, poor prognosis, acute kidney injury, venous thromboembolism, death, and progression to critical illness." (PMID 38783947, 2024). "With the help of this study, we concluded that prompt corticosteroid treatment in COVID-19 patients is linked to a significant drop in CRP levels within 72 hours after therapy." (PMID 38304653, 2024). "Older age, male gender, presence of comorbidities, and high CRP, were associated with the risk of severe cases, while the rs12329760 dominant model was associated with a protective effect against COVID-19 severity in univariable analysis." (PMID 38263160, 2024). "Other reports and meta-analyses have been published on other biomarkers of disease severity, showing a significant association between lymphocyte count, CRP, procalcitonin, LD, and D-dimer and COVID-19 severity." (PMID 38907229, 2024). "Most blood markers were significantly associated with all-time mortality in COVID-19 patients, with the strongest association with peak CRP level, CRP on admission, and lowest albumin level (p < 0.001 for all)." (PMID 39266635, 2024).
COVID-19 (continued). "The statistical results indicated that serum lactate dehydrogenase (LDH), glucose and C-reactive protein (CRP) are sensitive markers with a diagnostic role in COVID-19, and lymphocyte (Ly) count, CRP, ESR and glucose were evidenced to be target markers in PCI." (PMID 38392603, 2024). "Previous studies showed higher inflammatory markers such as procalcitonin, D-dimer, interleukin-6 and CRP resulting in a “cytokine storm” or hyperinflammatory state, which is associated with COVID-19 disease severity." (PMID 38699405, 2024). "Corticosteroid treatment in COVID-19 patients is associated with reduced CRP levels within 72 hours after therapy." (PMID 38304653, 2024). "This suggests that the effect of BMI on PASC risk is not only mediated by inflammation (as indicated by the association of obesity at COVID-19 onset with raised TNFα, sCD163 and CRP at 21–24 weeks), but also by additional physiological and metabolic processes." (PMID 39008486, 2024). "Multivariate analysis demonstrated a robust association of COVID-19 severity and TaqI polymorphism in the recessive model even after adjusting for multiple confounders, including age, sex and CRP levels [Adj.OR:3.23, 95%CI:1.17-8.86, p = 0.023]." (PMID 38474855, 2024). "A comparison of HA’s diagnostic utility with other COVID-19 biomarkers revealed that ROC AUC for HA was lower than those for inflammatory markers: IL-6 (0.863 vs. 0.992), CRP (0.863 vs. 0.998), PCT (0.863 vs. 0.966), and ferritin (0.863 vs. 0.922)." (PMID 39685929, 2024). "Our own research has shown that among patients hospitalized for up to 12 months with COVID-19, being overweight is associated with elevated CRP levels, compared to normal weight and obesity." (PMID 39518325, 2024). "The findings of this comprehensive study demonstrate considerable evidence that there are associations between two polymorphisms of the CRP gene (rs1205 and rs1800947) with COVID-19 mortality." (PMID 38184750, 2024). "Patients with periodontitis had a higher risk of developing severe COVID-19 symptoms and higher levels of inflammatory markers, such as CRP." (PMID 38800223, 2024). "For each one-unit increase in CRP concentration, risk levels of severe events have been reported to increase by 5 % in patients with COVID-19." (PMID 38623185, 2024). "A study has found that inflammatory factors including IL-2, YKL40, IL-4, IL-6, IL-10, sCD40L, TNF-α, IL-1Ra, interferon-gamma (IFN-γ), and CRP, are associated with cognitive impairment in COVID-19 patients." (PMID 38012459, 2024). "In this retrospective cohort of COVID-19 patients on mechanical ventilation, an association was demonstrated between a decrease in serum levels of CRP and successful weaning from ventilation." (PMID 38597482, 2024). "It was demonstrated in this study that in patients diagnosed with COVID-19, CRP elevation upon admission was common and was associated with increased disease severity." (PMID 38905361, 2024). "In individuals with more severe infections, especially those with pneumonia and respiratory distress, several reports have demonstrated an association between COVID-19 severity and elevated inflammatory markers, particularly CRP." (PMID 38383361, 2024). "Previous studies have reported that lymphopenia, thrombocytopenia, and elevated values of LDH and CRP were all associated with increased severity and mortality in COVID-19 patients." (PMID 38504259, 2024). "Elevated CRP concentrations are associated with COVID-19 severity but are also typically reported in severe viral infections, including H1N1 influenza pneumonia." (PMID 39768627, 2024). "For instance, poor oral health was found to be correlated with increased CRP levels in COVID-19 patients, and retrospective studies have found an association between periodontitis and COVID-19 severity." (PMID 38246829, 2024).